VWF (von Willebrand factor)
Diseases named in the same sentence as VWF in open-access papers (continued):
Sharing a sentence is not in itself a finding about the gene and the disease.
cancer (187 papers, 1998 to 2026). A tumor composed of atypical neoplastic, often pleomorphic cells that invade other tissues. "The coding sequences (CDSs) of 27 genes linked to FVIII or VWF plasma levels in GWAS were analyzed in 28,794 individuals in the large population-based Malmö Diet and Cancer cohort study (MDC)." (PMID 40488174, 2025). "Among the suggested oncodriver genes Von Willebrand factor (VWF), typically expressed in endothelial cells and megakaryocytes, and has been linked in cancer metastasis." (PMID 39906820, 2025). "Blood flow can mechanically extend and activate VWF to bind platelets and associate intermolecularly with other VWF molecules in plasma or on the surface of endothelial cells, cancer cells, or platelets." (PMID 39282473, 2024). "Clusters were annotated based on expression of representative marker genes, as previously reported: those included EPCAM for epithelial cells, PTPRC for CD45-positive immune cells, VCAM1 for cancer-associated fibroblasts, and VWF for endothelial cells." (PMID 39122703, 2024). "Many roles of VWF in cancer have been reported, including cancer-associated thrombosis (CAT), cancer metastasis, cancer apoptosis, inflammation, vessel permeability, and angiogenesis." (PMID 39282473, 2024). "Only one VWF polymorphism is identified to influence cancer pathways, namely the intronic SNP rs73049469 (C>A)." (PMID 38785560, 2024). "They suggested the neurogenic locus notch homolog protein 1 (NOTCH1) and von Willebrand factor (vWF) as early biomarkers of DOX cardiotoxicity to address the clinically significant question of identifying cancer patients at risk for cardiotoxicity." (PMID 37296716, 2023). "VWF as a primary platelet ligand has been widely used as a biomarker for cancer and associated inflammation." (PMID 36105100, 2022). "Further experiments dissecting the role heparins have on affecting VWF accumulation, cancer thrombotic and metastasis risk are required prior to applying this to routine patient care." (PMID 35327035, 2022). "The pathophysiology of cancer associated AVWS is heterogenous with multiple different pathogenic mechanisms that ultimately results in increased VWF clearance from the plasma." (PMID 35327035, 2022). "Along with ADAMTS13, VWF in excess or in deficiency can lead to cancer-associated thrombosis or bleeding." (PMID 35327035, 2022). "HCC, another frequently surveilled cancer in at risk populations, was shown to be associated with a high VWF antigen to ADAMTS13 activity ratio in cirrhotic patients." (PMID 35327035, 2022). "For example, EC activation by high concentrations of acrolein, a metabolite of the anti-cancer drug cyclophosphamide, induces a complete loss of vWF in HUVEC." (PMID 33478148, 2021). "Our present study confirmed that cancer is associated with increased levels of both sP-selectin and vWF:Ag, two molecules from the endothelial WPB." (PMID 33292287, 2020). "Multivariate logistic regression revealed two independent risk factors related to DVT in cancer patients undergoing chemotherapy: vWF:Ag and ADAMTS-13." (PMID 33292287, 2020). "Some studies have demonstrated increased vWF plasma levels in cancer cells with a potential implication in thrombosis-associated risk." (PMID 31212608, 2019). "And high levels of plasma vWF were shown to be associated with cancer malignancy degree, overall survival rate, and poor prognosis." (PMID 30279208, 2018). "Regression analysis further suggested that vWF expression in cancer cells was associated with levels of cell differentiation (r = −0.4256, p < 0.05)." (PMID 29362409, 2018). "von Willebrand factor (vWF) is a major platelet ligand that has been widely used as a biomarker in cancer and associated inflammation." (PMID 29362409, 2018). "Because there was no manipulation of the level of mouse plasma vWF, the data strongly implicated cancer cell-derived vWF in stimulating cancer metastasis." (PMID 29362409, 2018).
cancer (continued). "vWF mediates platelet adhesion in damaged vessels, and has been implicated in angiogenesis, and cancer spread." (PMID 28704418, 2017). "In conclusion, these data describe a plausible mechanism underlying the role of VWF fibers in cancer-related VTE and metastasis." (PMID 27602496, 2016). "Additionally, vWF overexpression drives cancer aggressiveness and is associated with more advanced stages of the disease." (PMID 41528397, 2026). "Hydrodynamic forces could also induce intermolecular interaction (VWF self-association) between circulating VWF and surface attached VWF to promote binding of VWF with EC, platelets, and cancer cells." (PMID 39282473, 2024). "Additionally, high plasma VWF levels appear to be independent predictors of VTE in cancer patients, and this risk is largely mediated by increased endothelial VWF expression." (PMID 35327035, 2022). "It is theorized that VWF deficiency may result in the increased availability of platelet GPIba to promote cancer metastasis." (PMID 35327035, 2022). "Importantly, the increased plasma levels of VWF in patients with cancer have also been shown to be associated with a poorer prognosis." (PMID 33571850, 2021). "For instance, platelets and von-Willebrand factor (vWF) not only play vital roles in preventing blood loss following a blood vessel injury by facilitating coagulation, but also contribute to thrombosis as well as cancer metastasis." (PMID 34205695, 2021). "In different studies, high plasma vWF was associated with the occurrence of VTE in cancer patients." (PMID 34205695, 2021). "In conclusion, in this study we could demonstrate that levels of VWF antigen and ADAMTS‐13/VWF were strongly associated with the risk of VTE in cancer patients." (PMID 31294335, 2019). "Overall, this may identify VWF as a possible laboratory tool for risk stratification of cancer patients prone to develop VTE." (PMID 31294335, 2019). "In our hands, impaired NO-dependent function in the aorta was associated with up-regulation of vWF expression, suggesting a pro-thrombotic phenotype of dysfunctional endothelium in aorta, compatible with cancer-related activation of pro-thrombotic endothelial mechanisms." (PMID 29788918, 2018). "In all cancer studies, the mutations inFVIII,VWF, andADAMTS13were reported in 93 cancer studies." (PMID 29152610, 2017). "At the same time, the compound also activates endothelial release of VWF, which in turn obstructs biological mechanisms of cancer spread and may cause apoptosis of micrometastatic cells arrested in the target organ." (PMID 21470136, 2011). "VWF, elevated throughout chemotherapy, particularly in individuals with vascular disorders, could be used as a diagnostic strategy for early diagnosing vascular diseases in chemotherapy-treated cancer patients." (PMID 38987722, 2024). "Given that Clusters 3 and 4 were identified as being associated with poor outcome, integration of the cancer-associated transcript (e.g., VWF) levels and/or TME immunocyte (e.g., CD8+T-cells) ratios into this model may be useful in further refinement of these MCL subgroups." (PMID 36359790, 2022). "However, VEGF-A binding by the LMWH Tinzaparin with subsequent inhibition of luminal VWF fiber generation explained Tinzaparin's additional anti-metastatic potential and provides novel insights into the mechanisms underlying cancer-associated coagulation and metastasis." (PMID 27602496, 2016). "Promotion of metastases by VWF appears to have platelet-dependent and independent mechanisms in a number of cancers." (PMID 41536292, 2026). "Clots from patients with concomitant cancer had a significantly higher content of vWF (median 26 [IQR13‐38]% vs. 10 %, p < 0.0001) and H3Cit (median 0.11 [IQR0.02–0.46]% vs. 0.05 [0.00–0.28]% p = 0.027) than controls." (PMID 39760182, 2025). "The involvement of VWF in various cancers and cardiovascular diseases underscores its potential as a biomarker or therapeutic target." (PMID 40699668, 2025).
cancer (continued). "By providing a possibility for cancer cells to interact with platelets and with the endothelium, vWF is thought to contribute to cancer spread and metastasis." (PMID 39760182, 2025). "This suggests a mechanoregulatory role of VWF in mediating the interactions between VWF and these cells to promote cancer cell adhesion to blood vessels." (PMID 39282473, 2024). "Overexpressing hsa-miR-1972 with inhibited VWF expression notably affected the malignant tumor markers and angiogenic factors in BC." (PMID 39529627, 2024). "In this review, we will focus on the evidence indicating VWF functions in hematogenous cancer metastasis." (PMID 39282473, 2024). "VWF has been shown to be an important mediator in cancer cell adhesion and extravasation during hematogenous metastasis." (PMID 39282473, 2024). "For example, how does VWF contribute to vascular permeability and angiogenesis for cancer cell extravasation from blood vessels?" (PMID 39282473, 2024). "Several receptors on platelets, EC, and cancer cells have been proposed to provide attachment points for VWF on these cells, in which the major ones are platelet GPIbα, P-selectin, ανβ3 and αIIbβ3 integrins, and glycocalyx." (PMID 39282473, 2024). "Regulating VWF function under flow can change its interactions with cancer cells, platelets, and EC, and also control cancer cell development." (PMID 39282473, 2024). "Platelet integrin αIIbβ3, also known as the glycoprotein GPIIb/IIIa, is capable of interacting with VWF, cancer cells and EC to facilitate cancer cell adhesion to platelets and EC." (PMID 39282473, 2024). "How do various flow rates and patterns mediate VWF interaction with cancer cell to regulate its rolling, arrest, and adhesion on the EC surface?" (PMID 39282473, 2024). "We will also elucidate the connection between the mechanoregulatory role of VWF and cancer metastasis in the presence of blood flow." (PMID 39282473, 2024). "Without ADAMTS13 to cleave long VWF strings, the number of metastatic foci can significantly increase in ADAMTS13-deficient mice, suggesting these tethered VWF strings assist cancer cell adhesion on EC." (PMID 39282473, 2024). "How do hydrodynamic forces generated by various blood flow affect cancer cell mechanosensing, and how does VWF contribute to this process?" (PMID 39282473, 2024). "This indicates a self-propagation process where vWF binds and activates platelets, releasing more hyperadhesive vWF stored in α-granules, contributing to cancer progression." (PMID 39456895, 2024). "Such cancer cell-derived VWF has also been shown to promote the interaction of cancer cells with platelets and EC to enhance metastasis." (PMID 39282473, 2024). "Under physiological flow conditions, secretion from cancer cells and/or platelets can activate EC to quickly release VWF to form strings." (PMID 39282473, 2024). "They concluded that cancer cells with low heparan sulfate levels evade von Willebrand Factor recognition and are prone to metastasis." (PMID 38745860, 2024). "During hematogenous cancer metastasis, blood flow applies hydrodynamic forces on cells and biomolecules in the blood vessels, which can affect VWF assisted CTC adhesion to and extravasation from EC layer in blood vessel walls." (PMID 39282473, 2024). "vWF has been proposed as a method by which cancer cells achieve metastasis, in effect being carried to distant sites via attachment to vWF multimers." (PMID 38540234, 2024). "VWF’s involvement in the growth of HCC, its functional domain in cancer, and VWF’s interactions with platelets and miRNAs are also investigated." (PMID 39859975, 2024). "In this review, we will summarize the current knowledge of VWF function and the role of hydrodynamic forces in hematogenous cancer metastasis." (PMID 39282473, 2024).
cancer (continued). "Both circulating plasma VWF and VWF attached to the cell surface can contribute to cancer adhesion on the EC surface by binding to platelets, EC, and cancer cells through membrane proteins, including platelet GPIbα, P-selectin, integrins, and glycocalyx." (PMID 39282473, 2024). "Many blood cells and proteins can contribute to hematogenous cancer metastasis, such as platelets, leukocytes, and von Willebrand factor (VWF)." (PMID 39282473, 2024). "We also looked into von Willebrand factor, a glycoprotein involved in both primary hemostasis as well as cancer progression." (PMID 39268353, 2024). "Secreted VWF exists in two main forms in the bloodstream, circulating VWF in blood plasma and tethered VWF at the cell surface of EC, platelets, or cancer cells." (PMID 39282473, 2024). "Elevated plasma VWF levels often appear in cancer patients, suggesting an important role of VWF in cancer development." (PMID 39282473, 2024). "This is in line with clinical studies which showed elevated vWF levels in the plasma of cancer patients." (PMID 37296987, 2023). "We found that the abundance and length of the cell-surface-exposed HS chain coordinate the recruitment of plasmatic vWF to the cancer cell surface, which blocked, e.g., the binding of platelets." (PMID 37296987, 2023). "Patients with advanced cancer display platelet hyperreactivity, with a higher number of platelets stably adhering to von Willebrand factor (VWF) and greater platelet surface coverage compared with those patients with early-stage cancer." (PMID 37103014, 2023). "As indicated, rapid clearance of VWF can alternatively arise in the presence of some malignancies, where VWF is absorbed onto cancer cells, as well as some congenital disorders (e.g., VWD of type 1 ‘clearance’)." (PMID 36499042, 2022). "With this force-clamp assay, studies reveal how integrin mediates cell–cell adhesion in a dynamic environment such as cancer cell and endothelial cell, leukocyte, and von Willebrand factor (VWF) and platelets." (PMID 35171346, 2022). "Our data also show that vWF expression is related to immune scores and patient survival, suggesting vWF as a novel biomarker of the basic immune state and predicts long‐term survival in cancer patients." (PMID 35735060, 2022). "CD42a is a platelet surface membrane glycoprotein that functions as a receptor for von Willebrand factor and is used to mark platelet‐related extracellular vesicles with potential role in promoting cancer cell survival." (PMID 35343093, 2022). "A large population‐based study demonstrated the association between coagulation, inflammation and survival of cancer patients, indicating that increased mortality in cancer survivors is dependent on high vWF levels." (PMID 35735060, 2022). "Many of the top overexpressed (e.g., FSTL1, TNS1, DDR2, or VWF) or underexpressed genes were suggested to promote invasion and/or metastasis in different cancer types." (PMID 36359790, 2022). "Collectively, the evidence for VWF as a robust cancer biomarker, either alone or in combination with other markers, such as ADAMTS13, at present remain inconclusive." (PMID 35327035, 2022). "Elevated levels of VWF in the plasma have been reported in various cancers, including breast, bladder, prostate and ovarian carcinoma, compared to benign disease and normal healthy controls." (PMID 33571850, 2021). "Due to the significance of hemostasis, VWF plays a role in cancers by inhibiting angiogenesis and apoptosis." (PMID 33968738, 2021). "Some clinical studies have found that the increased expression of VWF often indicates poor prognosis for patients with cancer." (PMID 34582363, 2021). "The increased plasma VWF in patients with cancer is conventionally thought to originate from the activated endothelial cells and platelets." (PMID 33571850, 2021). "The von Willebrand factor (vWf) plays an important role in angiogenesis, cell proliferation and apoptosis, inflammation and cancer." (PMID 34564628, 2021).
cancer (continued). "In this review, we summarize the currently known functions of VWF in different cell types, thereunder ECs, megakaryocytes, platelets, vascular smooth muscle cells and osteoclasts as well as cancer and immune cells." (PMID 34572000, 2021). "The synthesis of large VWF multimers consumes a lot of energy and resources; thus, cancer cells must gain an advantage by producing VWF, which is mostly presumed to involve an increased potential for metastasis." (PMID 34572000, 2021). "For stroma, the marker genes used were VWF, ENG, and CDH5 (for endothelial cells), DCN, ACTA2, and FAP (for cancer-associated fibroblasts), and PTPRC, CD4, and CD163 (for leukocytes)." (PMID 33810510, 2021). "In support of this, many in vivo studies that utilise antibody treatment have also shown marked reduction of metastatic potential in cancer cells following the inhibition of GPIbα and GPIIb/IIIa receptor sites and VWF." (PMID 33571850, 2021). "For gastric adenocarcinoma, it was further shown that cancer cell-derived VWF can enhance metastasis by mediating cancer cell aggregation and interaction with platelets and ECs." (PMID 34572000, 2021). "In particular, some cancer cells are known to activate VWF expression to promote a more malignant phenotype (see Chapter 2.8)." (PMID 34572000, 2021). "More recently however, novel biological roles for VWF have been reported including in inflammation, angiogenesis and cancer cell biology." (PMID 33571850, 2021). "Several studies show vWF-dependent cancer cell adhesion to the endothelium is mediated by integrin receptors and facilitates extravasation during metastasis." (PMID 33365273, 2020). "With increasing cancer stage, both sP-selectin and vWF:Ag levels were increased, whereas ADAMTS-13 levels were decreased at the time of inclusion." (PMID 33292287, 2020). "The objective of this study was to investigate the roles of sP-selectin, vWF, and ADAMTS-13 as risk factors for the first episode of DVT in cancer patients undergoing chemotherapy." (PMID 33292287, 2020). "As the impact of VWF levels on risk of VTE was time‐dependent with the highest HR at baseline, its potential importance for prediction of cancer‐associated VTE at cancer diagnosis is emphasized." (PMID 31294335, 2019). "The levels of ADAM domain-containing protein 28 (ADAM 28) are upregulated in malignant tumors, and ADAM 28 derived from cancer cells cleaves and inactivates the pro-apoptotic endogenous agent VWF." (PMID 31638892, 2019). "In multivariable Cox regression analysis adjusting for possible confounding factors, both ADAMTS‐13 and VWF alone and in combination remained statistically significant for survival probability in cancer patients (both P < 0.05 and P < 0.001, respectively)." (PMID 31294335, 2019). "In the present cancer patient cohort a clear association between elevated levels of VWF and decreased levels of the ADAMTS‐13/VWF ratio and occurrence of VTE was found." (PMID 31294335, 2019). "Low ADAMTS‐13 (a disintegrin‐like and metalloproteinase with thrombospondin type 1 motif 13) and increased von Willebrand Factor (VWF) levels in cancer patients have been described numerously." (PMID 31294335, 2019). "This is in accordance with the literature, which frequently describes lower ADAMTS‐13 and higher VWF levels in cancer patients, often also in a stage‐dependent intensity." (PMID 31294335, 2019). "Results for VWF remained statistically significant for prediction of VTE in cancer patients after adjusting for possible confounding factors in two multivariable models (Models 1 and 2)." (PMID 31294335, 2019). "Cancer patients have been shown to have higher VWF levels and lower ADAMTS‐13 levels than the general population, often also in a stage‐dependent intensity." (PMID 31294335, 2019). "The cancer cell-derived vWF provides a source of plasma vWF, in addition to endothelial cells that are the main source of vWF in the circulation." (PMID 29362409, 2018).